PRL (prolactin)
Diseases named in the same sentence as PRL in open-access papers (continued):
Sharing a sentence is not in itself a finding about the gene and the disease.
breast cancer (continued). "Expression of prolactin has been demonstrated by in situ hybridisation and immunostaining in the epithelial component of over 90% of human breast cancer samples." (PMID 18681966, 2008). "Exogenous prolactin is mitogenic and antiapoptotic in breast cancer cells, and overexpression of autocrine prolactin cDNA in breast cancer cell lines has been shown to stimulate their growth and to protect against chemotherapy-induced apoptosis." (PMID 18681966, 2008). "There is existing evidence showing a survival role for prolactin in breast cancer cells, and for STAT5 in normal mammary epithelial cells." (PMID 19014541, 2008). "As HSP90α is a central therapeutic target for breast cancer treatment, this also elevates the importance of prolactin and specifically identifies one mechanism for its contribution to breast cancer." (PMID 19014541, 2008). "We identified a number of genes in our screen of breast cancer SKBR3 cells whose expression either increased or decreased in response to prolactin." (PMID 19014541, 2008). "Elevated first trimester oestrogen, androgen and prolactin concentrations in first full-term pregnancies, and elevated oestrogen, androgen and progesterone concentrations in pregnancies occurring at younger ages may be consistent with these hormones acting to reduce later breast cancer risk." (PMID 18766187, 2008). "Prolactin (PRL) is a mitogenic hormone similar to growth factors and rat mammary tumour express PRL messenger RNA and acts as a local growth factor that stimulates proliferation of mammary tumours." (PMID 18045456, 2007). "One of the glandular secretory proteins, prolactin, stimulates tumor growth and motility of human breast cancer cells and a recent review suggested that antagonizing prolactin should be evaluated as a tumor treatment." (PMID 17263869, 2007). "This suggested that the breast cancer cell lines must be producing their own prolactin as has been demonstrated previously." (PMID 15213724, 2004). "To confirm these observations, we then induced apoptosis and showed for the first time that exogenously added prolactin does act as a potent survival factor against C2-ceramide-induced apoptosis in breast cancer cell lines." (PMID 15213724, 2004). "In support of prolactin being a potent survival factor, we observed that the sensitivity of the breast cancer cell lines to the physiological inducer of apoptosis, C2-ceramide, appeared relative to the levels of endogenous prolactin that they contained." (PMID 15213724, 2004). "The aims of this study were to use these models to assess the role of prolactin in breast cancer cell growth and survival with a view to increasing our understanding of its obvious potential as a therapeutic target." (PMID 15213724, 2004). "Recent studies showing inhibition of cell growth and survival of breast cancer cells in the presence of prolactin blocking antibodies and receptor antagonists also support an autocrine/paracrine loop of locally produced prolactin." (PMID 15213724, 2004). "It has been conclusively demonstrated that human normal breast and breast cancer cell lines produce their own prolactin." (PMID 15213724, 2004). "We confirmed that the breast cancer cells lines we were studying did contain prolactin and that the levels varied between lines." (PMID 15213724, 2004). "In summary, we have shown that prolactin acts as a potent survival factor for human breast cancer cell lines, which has also been demonstrated for Nb2 lymphoma cells, thymocytes and the PC3 prostate cancer cell line." (PMID 15213724, 2004). "A hormone such as prolactin, whose normal action is to promote cell proliferation and differentiation, was soon identified as a potential candidate for the progression of breast cancer, where cells are proliferating and surviving inappropriately." (PMID 15213724, 2004). "Using established models of apoptosis of human breast cancer cell lines, we assessed the role of prolactin in breast cancer cell growth and survival." (PMID 15213724, 2004).
breast cancer (continued). "The failure of these clinical trials resulted in a diminished interest in prolactin as a therapeutic target in human breast cancer." (PMID 15213724, 2004). "This is supported by a clinical study, which described how inhibiting prolactin secretion using agents such as bromocriptine enhanced the efficacy of chemotherapeutic drugs for the treatment of breast cancer." (PMID 15213724, 2004). "Transgenic female mice overexpressing the rat prolactin gene spontaneously developed mammary carcinomas." (PMID 15213724, 2004). "In this paper, we examine the possibility that the PRL/PRL-R is involved in protection of CD3+ immune cells from apoptosis in patients with breast cancer." (PMID 12698200, 2003). "To evaluate the role of PRL and PRL-R in spontaneous apoptosis of circulating T cells observed in cancer patients, we measured these parameters in patients with breast cancer and in normal controls." (PMID 12698200, 2003). "In order to determine if expression of the CIS protein was dependent on serum factors, including prolactin and GH, the breast cancer lines were deprived of serum for 12 h before harvesting for immunoblot analysis." (PMID 12888825, 2003). "Epidemiologic evidence indicates a role of prolactin in both the pathogenesis and progression of breast cancer." (PMID 12888825, 2003). "Expression of PRL-R on the surface of T cells was comparable in patients with breast cancer and NC, but PRL plasma levels in patients were significantly lower (P<0.05)." (PMID 12698200, 2003). "Both can also be synthesised locally in the mammary gland, and antagonists of the prolactin and growth hormone (GH) receptors are able to inhibit proliferation of breast cancer lines." (PMID 12888825, 2003). "Two recent papers demonstrate that prolactin plays an important role in the induction and progression of mammary tumours." (PMID 9888458, 1999). "Growth of the transplantable EMR-86 rat mammary carcinoma depends on elevated prolactin levels which are induced by oestrogenic stimulation of the pituitary." (PMID 8630280, 1996). "Serum prolactin concentrations were measured in 135 postmenopausal patients with advanced breast cancer prior to their treatment with one of 3 endocrine therapies: aminoglutethimide (AG), tamoxifen (T) + AG, or T + AG + danazol." (PMID 6860546, 1983). "Serum testosterone, 17 beta-oestradiol, luteinising hormone (LH) and prolactin were measured in 28 postmenopausal breast cancer patients after mastectomy and in 30 postmenopausal normal controls." (PMID 6824571, 1983). "We conclude that direct as well as indirect evidence has been found for the involvement of prolactin in the growth of transplanted, hormone-dependent GR mouse mammary tumours." (PMID 577471, 1977). "Administration of ovine prolactin alone supported growth of hormone-dependent GR mouse mammary tumours." (PMID 577471, 1977). "The serum prolactin levels in the patients with breast cancer, gynaecomastia or cystic mastitis were observed to be similar to that in normal women." (PMID 2274, 1975). "Serum prolactin concentrations were measured by radioimmunoassays in 98 patients with established carcinoma of breast, 12 patients with cystic mastitis and 10 patients with gynaecomastia and compared with that of age matched normal control women." (PMID 2274, 1975). "Patients prescribed risperidone, paliperidone, and amisulpride, which possess prolactin-elevating properties, exhibited a 1.96-fold increased risk of breast cancer compared to the non-schizophrenic cohort." (PMID 40465597, 2025). "However, in cooperation with transforming growth factor-α (TGF-α), PRL mammary tumors were induced in 100% of male bitransgenic mice." (PMID 40160874, 2025). "DMBA-induced breast cancer had higher estrogen and prolactin levels than controls." (PMID 40097629, 2025). "Other studies show a 70% higher risk of breast cancer in patients with prior breast disease, than those without PLRrs are a major mediator of the cellular effects of PRL." (PMID 40160874, 2025).
breast cancer (continued). "There is also evidence suggesting that prolactin may have a protective effect and suppress breast cancer cell growth." (PMID 38554178, 2025). "Indeed, efforts have been directed to block PRL as a therapeutic avenue in breast cancer, including the generation of PRL antagonists (Del1-9-G129R-hPRL, G129R-Prl) and PRLR antagonist (LFA102)." (PMID 40157909, 2025). "The central role of PRL in MEC differentiation suggests that it may also play a differentiation role in breast cancer, and this may contribute to its anti-tumorigenic effects." (PMID 40157909, 2025). "Beyond its roles in microtubule dynamics, NEK3 is also involved in various signaling pathways involved in breast cancer progression, including prolactin signaling, estrogen receptor signaling, Rho GTPase signaling, cell cycle regulation, and PI3K/AKT signaling." (PMID 41154634, 2025). "A preclinical study demonstrated that prolactin could suppress cellular growth or metastasis of breast cancer, and another study indicated that the 16-kDa prolactin isoform, a prolactin fragment, had anti-angiogenic effects in in vivo experiments." (PMID 38554178, 2025). "Similarly, in breast cancer, PRL/PRLR signaling has been shown to suppress breast cancer stem cell populations." (PMID 40157909, 2025). "Notably, PRL also promoted distinct morphological features in breast cancer cellular models, with acinar-like structures in HR+ breast cancer cells and induced epithelial-like features in claudin-low mesenchymal TNBC cells." (PMID 40157909, 2025). "The role of PRL in breast cancer is still to be fully characterized." (PMID 40157909, 2025). "Therefore, targeting PRL/PRLR pathway as a therapeutic avenue in breast cancer has been a topic of interest for decades." (PMID 40157909, 2025). "Emerging evidence suggests that melatonin's regulatory influence on PRL levels may critically impact breast cancer pathogenesis, particularly in hyperprolactinemic conditions." (PMID 41370498, 2025). "This soluble isoform has been characterized in human breast cancer cell lines and seemingly functions as a regulatory mechanism for the bioavailability and signaling of extrapituitary PRL, which is why it is also known as “PRL binding protein” in the extracellular domain." (PMID 40806464, 2025). "PRLR pathway activated by PRL could significantly decrease sensitivity of ERα-positive breast cancer cells to tamoxifen." (PMID 38898487, 2024). "In the mammary cancer cells, prolactin stimulation leads to labile iron pool accumulation." (PMID 39201626, 2024). "Thus, our current data on pTyr-PAK1 regulation of EMT bring insight into the role of PAK1 and PRL in human breast cancer." (PMID 38660565, 2024). "The role of PRL in breast cancer has been confirmed at the cellular levelin vitro, with multiple transgenic and knockout modelsin vivo, and through epidemiologic analysis (reviewed in Tworoger and Hankinson 2006, Tworoger and Hankinson 2008, Clevenger and Rui 2022, Schuler and O'Leary 2022)." (PMID 38933712, 2024). "Results show distinct roles of prolactin in mammary cancer cells and macrophages." (PMID 39201626, 2024). "Our data further showed that PRL could decrease tamoxifen sensitivity of breast cancer in a 3D spheroids model." (PMID 38898487, 2024). "Here we first show that PRL-activated pTyr-PAK1 enhances breast cancer growthin vivo." (PMID 38660565, 2024). "In addition, some studies indicate the role of prolactin and its receptor in the biology of breast cancer." (PMID 38886335, 2024). "Interestingly, when macrophages and mammary cancer cells were co-cultured, we observed a direct labile iron pool transfer from macrophages to the cancer cells with prolactin treatment." (PMID 39201626, 2024).
breast cancer (continued). "Compared with 8173 matched controls, the odds of breast cancer increased in women with prior exposure to prolactin-increasing antipsychotics for 1–4 years (adjusted odds ratio [aOR] = 1.20, 95% confidence interval [CI] = 1.03–1.41), and for ≥ 5 years (aOR = 1.47, 95%CI = 1.26–1.71)." (PMID 38687213, 2024). "Breast cancer is more prevalent in women with severe mental illness than in the general population, and use of prolactin-increasing antipsychotics may be a contributing factor." (PMID 38687213, 2024). "However, prolactin stimulation in both mammary cancer cell lines significantly increases labile iron pools via the upregulation of CD44." (PMID 39201626, 2024). "Tamoxifen up-regulates PRLR protein level in breast cancer cells and activation of PRLR pathway by PRL could decrease drug-sensitivity of breast cancer cells to tamoxifen." (PMID 38898487, 2024). "Elevated prolactin is not known to affect development of any tumor types aside from a modest association with breast cancer and there is no biological knowledge supporting a connection to the incidence of any kinds of lung tumors." (PMID 38440945, 2024). "Further, the claims data also lack detail on serum prolactin levels which are the hypothesized mediator between HPD use and potential risk of breast cancer." (PMID 38595824, 2024). "Similarly, some researchers also reported the role of PRLR in the etiology and proliferation of prolactin (PRL)-induced breast cancer (Kavarthapu, Anbazhagan & Dufau, 2021)." (PMID 39253602, 2024). "However, in vitro and in vivo studies support that prolactin is involved in processes related to late-stage carcinogenic effects of breast cancer, including increasing cell proliferation and reducing apoptosis." (PMID 38595824, 2024). "It indicated that local prolactin produced by breast cancer cells could affect the response and prognosis of tamoxifen treatment." (PMID 38898487, 2024). "However, emerging evidence suggests potential involvement of PRL in breast cancer (BC) pathogenesis, particularly in its capacity to promote tumor growth." (PMID 38898487, 2024). "Although pSTAT5 can be activated through the PRLR pathway, we did not see the same increased risk of a PRLR positive breast cancer with elevated prolactin." (PMID 36882838, 2023). "The role of PRL and PRL receptors (PRLR) in tumor progression and tumorigenesis is well known, and several studies have manifested the regulatory involvement of PRLR in medication responsiveness and the prometastatic effect of PRL on breast cancer and other gynecological cancers." (PMID 37168445, 2023). "In breast cancer, both PRL and PRLR are extensively expressed." (PMID 37834225, 2023). "There are four main theories explaining how pregnancy may provide protection against breast cancer:Hormonal Fluctuations: Pregnancy involves fluctuations in hormone levels, such as estradiol, prolactin, and growth hormone." (PMID 37580469, 2023). "However, more studies are needed to understand the role of PRLR and prolactin in canine mammary tumors, including their protein expression levels among the subtypes and subgroups." (PMID 37789381, 2023). "In addition, JAK2 and STAT5A overexpression cooperatively reverses EMT and promotes differentiation in human breast cancer cells, which explains the suppression of invasion of prolactin-activated STAT5A in mammary cancer cells." (PMID 38124049, 2023). "Moreover, using L-dopa or ergot compounds to inhibit prolactin has been observed to achieve bone relief in women with metastatic breast cancer, which increases the possibility of prolactin-promoting breast cancer." (PMID 36945262, 2023). "No significant heterogeneity of the prolactin/breast cancer association was observed for any of the other combinations of two tumor markers (p-heterogeneity: 0.07 to 0.88)." (PMID 36882838, 2023). "Thus, PRL factors as well as EGFR signaling pathways interact in breast cancer development and progression." (PMID 37415164, 2023).
breast cancer (continued). "Among postmenopausal women, plasma prolactin levels were positively associated with breast cancer risk irrespective of PRLR, pSTAT5, or pJAK2 expression (all p-heterogeneity ≥ 0.21)." (PMID 36882838, 2023). "The finding was that 1 to 4–5 years of cumulative exposure to prolactin-sparing antipsychotics (clozapine, quetiapine, or aripiprazole), i.e., small amounts of extra prolactin, did not increase the risk for breast cancer." (PMID 37759839, 2023). "The obtained results revealed that long-term exposure to PRL-increasing antipsychotics, but not to PRL-sparing antipsychotics, was significantly associated with increased odds of breast cancer." (PMID 36833950, 2023). "Prolactin (also called luteotropin) is described as the third hormone in breast cancer." (PMID 37789381, 2023). "In contrast, the role(s) of PRL in the biology of established clinical breast cancers remains unclear." (PMID 35784527, 2022). "In this review, we provide an overview of the current understanding of the transcriptional regulation of PRLR and signal transduction in physiological and pathological modalities in mammary glands with special emphasis on the role of PRL/PRLR signaling in breast cancer." (PMID 36187116, 2022). "In addition, it has been described that in breast cancer cells prolactin increases the expression and the activity of CPTA1 in relation to normal cells." (PMID 36308613, 2022). "Collectively, in breast cancer accumulating data implies PRL/PRLR as a clinically relevant potent differentiation pathway limiting the tumorigenic phenotype and thus may serve as a potential pro-differentiation therapeutic candidate." (PMID 36157462, 2022). "In the study nested within the Nurses’ Health Study, PRL levels predicted breast cancer risk independent of estrogen." (PMID 35784527, 2022). "We aimed to confirm whether PRL plays a crucial role in the pathophysiology of antipsychotic-induced breast cancer." (PMID 36591471, 2022). "Interestingly, our original work investigating the role of PRL in breast cancer BC revealed PRL to act a potent suppressor of the EMT process, further inhibiting the invasive capacity of breast cancerBC cells." (PMID 36157462, 2022). "Also, PRL was found to suppress induction of the cytokeratin-5 (CK5)-positive stem-like population in breast cancer cells both in vitro and in vivo." (PMID 36157462, 2022). "The JAK2 pathway plays a critical role in PRL-induced proliferation of normal mammary epithelial cells, as well as in human breast cancer cells, and we have previously shown that PRL induces proliferation of different breast cancer cells." (PMID 35089929, 2022). "In previous studies, some have reported the association between PRL and antipsychotics and suggested antipsychotics as a potential risk factor for breast cancer; however, they failed to provide a confirming conclusion." (PMID 36591471, 2022). "For example, prolactin could prevent hepatocellular carcinoma, but in breast cancer, prolactin could promote cancer progression." (PMID 36456906, 2022). "Importantly, functional investigations of these PRL-downregulated genes identified novel players in breast cancer." (PMID 36157462, 2022). "Supplemental estrogen accelerates PRL-driven mammary cancers in the NRL-PRL model." (PMID 35784527, 2022). "Together, these reports suggest that PRL may modulate inflammation and/or immunotolerance during tumorigenesis, with potential to contribute to a permissive environment for development of breast cancer." (PMID 35784527, 2022). "Altogether, these findings implicate that PRL of endocrine or tumor source is not a risk factor in breast cancer but rather a marker of more differentiated and less aggressive tumors and is a potential therapeutic agent." (PMID 36157462, 2022). "We then address the more controversial role(s) for PRL in established breast cancers." (PMID 35784527, 2022).